CD4 (CD4 molecule)
Diseases named in the same sentence as CD4 in open-access papers (continued):
Sharing a sentence is not in itself a finding about the gene and the disease.
autoimmune disease (continued). "Conventional T cells (Tconv, CD4+CD25-CD127+) are considered to be main players in maintaining a normal immune response and exert autoreactivity in autoimmune diseases like MS." (PMID 25360562, 2014). "Treg cells, defined by the expression of CD4, CD25, and the key transcription factor Foxp3, have an important role in immune suppression and protection from autoimmune diseases." (PMID 24177566, 2013). "CD4+CD25+Foxp3+ Treg cells are a specialized Th cell subset that is engaged in maintaining peripheral tolerance, preventing autoimmune diseases, and limiting chronic inflammatory diseases by suppressing and regulating the effector function of Th cells." (PMID 24187560, 2013). "Previously, the expression of Kv1.3 potassium channels, the target of T cell-mediated autoimmune diseases, was decreased by scorpion toxin ADWX-1 blocker in CD4+CCR7- T cells overexpressing Kv1.3 channels." (PMID 24386436, 2013). "Of note, the expansion of CD4+CD28null T cells is a common finding in many unrelated proinflammatory conditions like ESRD, HIV, infection and autoimmune diseases." (PMID 24288592, 2013). "Regulatory T cells, mostly defined as CD4+ with high expression of CD25, usually increase with age, but obviously have less suppressive function on inflammatory mechanisms in some autoimmune diseases." (PMID 24006909, 2013). "Consistent with the potential therapeutic role of regulatory T (Treg) cells against various autoimmune diseases, KD treatment in EAE mice resulted in a tendency toward increased CD4+CD25+Foxp3+ Treg cells." (PMID 22567104, 2012). "In experimental autoimmune diseases, the balance between the Th17 effector cells and the two regulatory T cells, CD8+CD122+ and CD4+CD25+, seems to regulate both the occurrence and severity of tissue destruction and functional failure." (PMID 22876245, 2012). "So called naturally occurring Treg (CD4+CD25+FOXP3+ T cells) are essential for maintaining peripheral tolerance, preventing autoimmune diseases and limiting chronic inflammatory diseases." (PMID 21494636, 2011). "In marked contrast to IL-2Rβ−/− mice, the IL-2Rβ transgene restored the normal levels of CD4+CD25+ nTreg and prevented the onset of a fatal autoimmune disease, further reinforcing the notion that IL-2 plays a critical role in the thymic development of nTreg." (PMID 21647403, 2011). "Using three different murine autoimmune disease models, we have demonstrated that MHC class II dextramers permit ex vivo enumeration of self-reactive CD4 T cells with specificity." (PMID 21767394, 2011). "IL-2 mediates the cooperation of memory-like CD4+ and CD8+ T cells in the breakdown of cross-tolerance, resulting in effector cytotoxic T lymphocyte differentiation and the induction of autoimmune disease." (PMID 20856822, 2010). "CD4+CD25+ Treg cells suppress activated T cells, and this immune suppression is vital in preventing autoimmune diseases." (PMID 19116909, 2009). "IL-17 is produced by CD4+ TH17 cells, which play a role in the etiology and pathology of autoimmune disorders." (PMID 20049214, 2009). "Recent studies have increasingly emphasized the importance of CD4+,CD25+ regulatory T cells in autoimmune disease." (PMID 18576325, 2008). "Intrinsic Treg, i.e. specifically described as CD4+CD25+foxP3+ T cells, which prevent autoimmune disease, are expanded in NOD mice only after blocking CD40–CD154 interaction." (PMID 18446238, 2008). "Furthermore, AGEs stimulate the proliferation of CD4(+)CD28(-) T cells, which play a role in autoimmune diseases." (PMID 40565966, 2025). "In a model of passive experimental autoimmune encephalomyelitis, IL-1β-, TNFR-, and Fas-deficient recipients all failed to develop diseases, suggesting that memory CD4+ T cell–induced IL-1β is a critical driver of autoimmune disease pathology." (PMID 40279312, 2025).
autoimmune disease (continued). "Notably, distinct regulatory CD4+ T cell subsets exhibit organ‐specific tropism and selectively control different autoimmune conditions, while CD4+CD25+ Tregs are pivotal in maintaining tolerance and preventing autoimmune disorders." (PMID 40757098, 2025). "Collectively, these observations suggest that Piezo1 is essential for effector T-cell persistence, and without a continuous pool of newly activated CD4+ T cells, these Piezo1cKO T cells are incapable of inducing phenotypic autoimmune diseases." (PMID 39492686, 2025). "Although the search for key neoantigens for the disease is difficult, researchers have demonstrated that adaptive immune response disorders, especially the abnormal stimulation of CD4+ and CD8+ T cells, are pivotal in the onset and progression of autoimmune diseases." (PMID 40538197, 2025). "In addition, previous studies showed that exposure to chronic autoantigen seems to favor the development of CD4 + TEM while hindering CD4 + TCM cell formation, such as in chronic infection and different autoimmune diseases." (PMID 39004660, 2024). "We show that specific payloads can tune the degree to which suppression is targeted to CD4+ or CD8+ cells, a feature that could be useful for addressing autoimmune diseases driven by different mechanisms." (PMID 39636990, 2024). "In addition, our meta-analysis revealed sex- and age-related CD4+ T cell changes, with new observations such as increased Tnaive MX1 and Tem (Tph) in females, potentially contributing to gender differences in autoimmune disease incidence." (PMID 38359792, 2024). "The investigation of CD4 and CD8 cells, along with the examination of activated CD4 and CD8 cells, holds paramount significance in unraveling the fundamental mechanisms of autoimmune diseases such as neuroimmunological or other inflammatory disorders and aiding in their diagnosis." (PMID 39273504, 2024). "In MS and other experimental autoimmune disorders, researchers have discovered the beneficial effect of T cell vaccination, which stimulates the occurrence of CD8+ Tregs, and results in the selective downregulation of self-reactive CD4+ T cells." (PMID 38390334, 2024). "After the discovery of CD4 Treg cells that express high levels of CD25 on the surface, this approach was resurrected by several groups to selectively target the activation and expansion of these cells for therapeutic intervention in autoimmune diseases." (PMID 39320047, 2024). "Given that the immunomodulatory effects of MSCs have been shown to be most effective on CD4+ T cells, it is not surprising that MSCs have been utilized in the highest number of clinical trials aimed at treating autoimmune diseases." (PMID 39676874, 2024). "CD4+NKG2D+ T cells are also thought to be cytotoxic cells and have been shown to be involved in rheumatoid arthritis (RA), Wegener’s granulomatosis (WG) and multiple sclerosis (MS), among other human autoimmune diseases." (PMID 38515134, 2024). "Like in heterologous infectious challenges, CD4+ TIA cells are thus preferentially recruited to the site of autoimmune inflammation, where they can be activated in a TCR-independent manner to produce IFN-γ and contribute to autoimmune disease." (PMID 38838013, 2024). "Previous animal studies have shown that EAM is an autoimmune disease mainly mediated by CD4+ T lymphocytes but not CD8+ T lymphocytes." (PMID 37901475, 2023). "Effector CD4+ T cells, particularly interferon-γ (IFN-γ) producing T helper 1 (TH1) cells and interleukin-17 (IL-17) producing TH17 cells, are the major immunopathogenic cells that contribute to the development of autoimmune disorders." (PMID 37851814, 2023). "The primary function of CD4+CD25+ Tregs is to maintain the body’s immune tolerance and suppress the immune response thus maintaining and regulating the body’s immune homeostasis, which is increasingly studied in inflammation, autoimmune diseases, and tumors." (PMID 37731506, 2023).
autoimmune disease (continued). "Moreover, an increased percentage and absolute count of PD-1-expressing CD3+CD4+ and CD3+CD8+ T cells have been previously reported in autoimmune diseases." (PMID 37034572, 2023). "HELIOS-deficient CD8 Tregs failed to protect mice against autoimmune disease, highlighting a potential shared role for HELIOS in CD8 Tregs and CD4 Tregs." (PMID 38187391, 2023). "We previously reported identification of this non-conventional CD4+ helper T cell subset as the dominant tissue-infiltrating CD4+ T cell subset driving inflammation in several autoimmune diseases including IgG4-related disease and systemic sclerosis." (PMID 38077321, 2023). "Overall, previous studies have shown the functions of MP CD8+ T cells in disease, but the role of MP CD4+ T cells in autoimmune disease has not yet been studied." (PMID 37121980, 2023). "The role of CD4+ and/or CD8+ TSCM in the pathogenesis of autoimmune diseases." (PMID 37497231, 2023). "Recent studies demonstrated that CD4+ and/or CD8+ TSCM cells play a vital role in the pathogenesis of autoimmune diseases such as systemic lupus erythematosus (SLE), aplastic anemia (AA), autoimmune uveitis, T1D, rheumatoid arthritis (RA), and immune thrombocytopenia (ITP)." (PMID 37497231, 2023). "Tim-3, one of the important members of the Tim family, plays a key role in regulating the differentiation and proliferation of CD4+ T and CD8+ T cells and is involved in the occurrence and development of many diseases such as tumors, infections, and autoimmune diseases." (PMID 38126537, 2023). "Collectively, those studies suggest that antigen-nonrelated CD4+ T cells can contribute to disease onset or progression with antigen-specific T cells in various autoimmune diseases." (PMID 37121980, 2023). "It has been shown that CD4+ T cells are participants in the pathogenesis of psoriasis, and their elevation coupled with a decrease in Tregs results in a significant increase in the CD4/CD8 ratio, an identifying characteristic of many autoimmune diseases." (PMID 35736648, 2022). "Five peptides were chosen that were 1) not specifically described to be preferential CD4 T cell targets in autoimmune disease, 2) contained an arginine within the predicted binding core region and 3) showed a range of predicted binding affinities." (PMID 36544781, 2022). "Similar expression of TLR9 in CD4+ T cells and B cells indicate that even CD4+ T cells could play a role by involving TLR9 under autoinflammatory and autoimmune disease conditions." (PMID 37406035, 2022). "Beyond CD4+-T cells, multiple types of immune cells, including CD8+ cytotoxic T cells, macrophages, dendritic cells, B lymphocytes, were all dramatically activated in Foxp3cre;Rbx1fl/fl mice, indicating a typical phenotype of autoimmune disease." (PMID 35641500, 2022). "A long-standing difficulty in treating autoimmune disease, such as MS, is the lack of understanding of inflammatory tissue-infiltrating CD4 cells." (PMID 35178050, 2022). "Further, they are involved in CD4+ T cell expansion, but may also positively regulate CD8+ T cells, as it has been shown in mouse models of autoimmune diseases." (PMID 35203348, 2022). "Notably, the ratio of CD4 T cell to CD8 T cell was dramatically higher in JIA patients than in healthy controls, indicating that JIA was an autoimmune disease." (PMID 36160781, 2022). "Thus, it would be valuable to test the effect of TNFR2 blockade on Tregs and other CD4+ T cell subpopulations and on the levels of cytokines they produce to potentially uncover biological mechanisms that may help develop novel therapeutic strategies to treat RA or other autoimmune diseases." (PMID 36012570, 2022). "It was also shown that WRS inhibited the proliferation of hUCB-MSCs derived CD4+T cells by promoting apoptosis, which indicated that WRS might have a therapeutic effect in autoimmune diseases by regulating the hyper-activation of regulatory CD4+ T cells." (PMID 36017335, 2022).
autoimmune disease (continued). "Recently, T peripheral helper (CD3+CD4+CD45RA−CXCR5−PD-1hi, TPH) cells were identified as helper T cells that promote antibody production from B cells in the inflamed tissues of patients with rheumatoid arthritis and other autoimmune diseases." (PMID 34991631, 2022). "Together, these data show that generation of ANAs, without active autoimmune disease, correlates with distinct changes in the CD4+ T cell compartment in young patients." (PMID 36311777, 2022). "Unequivocal description of inflammatory changes is lacking; OA is not considered an autoimmune disease; yet, infiltration of CD4+ T cells has been shown in early stages." (PMID 35159924, 2022). "Importantly, the tolDCs are capable of inducing regulatory T cells (Tregs), as well as quelling autoreactive CD4+ and CD8+ T cells in an antigen-specific manner, providing a precision therapeutic approach for autoimmune diseases." (PMID 36510261, 2022). "After the exclusion of people with comorbidities or conditions potentially affecting the immune recovery (i.e., cirrhosis, autoimmune diseases and/or malignancies, previous CVD events, N = 59), we found that the CD4/CD8 ratios showed similar increases to those of the whole study population." (PMID 36366413, 2022). "Although excess CD4+ T cell response leads to autoimmune diseases, reduced CD4+ T cell activation does not protect the body from pathogen infections." (PMID 33941870, 2021). "However, this CpG site is also an eQTM for five other genes in CD4+ T cells (TAGLN2, SLAMF8, DUSP23, PHYIN1 FCRL6), several of which have established autoimmune disease connections." (PMID 34946847, 2021). "Of particular interest have been regulatory T cells (Tregs), which were identified in a landmark study in 1995 showing a subpopulation of CD4+ T cells that expressed the IL-2 receptor (CD25) and were responsible for preventing the development of autoimmune disease." (PMID 33737934, 2021). "The results showed that the Crohn’s disease’s twin (twin 2) had no antibody detection and reduced activation of CD4+ T cell responses, unlike the twin without the autoimmune disease (twin 1)." (PMID 34834950, 2021). "In many conditions, such as chronic inflammations and infectious or autoimmune diseases, CD28 expressions were reduced or diminished (CD4+CD28null); however, surrogate co-stimulatory molecules were present on these cells, resulting in alterations in immune responses." (PMID 33808849, 2021). "T-reg cells could be of major importance in autoimmune diseases, such as RA, by suppressing several immune cells, including CD8+ and CD4+ T-cells, antigen presenting cells (APCs), natural killer (NK) cells, and dendritic cells." (PMID 33461620, 2021). "Along these lines, recent work reported that a group of autoimmune diseases (RA, SLE, GD and, SSc) share the hypomethylation of IFN-related genes in CD4+ T cells and could be used as a signature for various autoimmune disorders." (PMID 34769338, 2021). "The absence of OX40 and CD30 co-stimulatory signals prevents CD4 T cell-driven autoimmune disease and anti-tumor CD8 T cell responses can be achieved in Foxp3-deficient mice." (PMID 33527196, 2021). "If, similar to CD4 Tregs, these neuro-regulatory CD8 T cells are more resistant to sepsis-induced lymphopenia this may be an additional mechanism by which autoimmune disease could be suppressed." (PMID 33191915, 2020). "Thus, the VPAC1 loss observed in CD4+CD28− T cells of these patients could be related with the fact that expanded senescent Th cells can produce large amounts of pro-inflammatory cytokines and also have cytotoxic potential in many inflammatory/autoimmune diseases." (PMID 33291545, 2020). "Our experimental work in mice has suggested that most, if not all, CD4+ T-cell specificities recognizing autoantigenic epitopes expressed by the target tissue of a given autoimmune disease can be re-programmed into Tr1 cells in vivo via pMHCII-NP therapy." (PMID 33574822, 2020).
autoimmune disease (continued). "Interestingly, IL-10R signaling and downstream STAT3 phosphorylation are defective in CD4+ T cells from patients with systemic lupus erythematosus and MS, suggesting that failure of T cell suppression by IL-10 may play an important role in autoimmune disease, including in the CNS." (PMID 32303238, 2020). "In the absence of effective regulation, Th1 CD4+ T cell responses can target self-peptides, resulting in autoimmune diseases such as Type 1 diabetes (T1D), Rheumatoid Arthritis (RA), and Systemic Lupus Erythematosus (SLE)." (PMID 33374787, 2020). "These subsets express the master transcription factor, FOXP3, and include Tr1 cells and CD4+CD25+ Tregs, which are the main population involved in maintaining the peripheral tolerance, preventing the autoimmune diseases and limiting the chronic inflammatory diseases such as CD." (PMID 31952431, 2020). "To further investigate the immunopathological role for this bystander response, we hypothesized that bystander-activated memory-like CD4+ T cells contribute to the development of EAE, a TH17-mediated autoimmune disease model of multiple sclerosis (MS)." (PMID 30755603, 2019). "For autoimmune diseases, the median TCR β-chain frequency in RA patients was increased tenfold, indicating marked contraction of the repertoire, and disease activity of RA was negatively correlated with the TCR repertoire diversity of CD4+ T cells." (PMID 30777078, 2019). "In order to recognize the commonalities of different autoimmune diseases, including GD, RA, SLE, and SSc, we collected Illumina Methylation 450K microarray data of 116 patients with GD/RA/SLE/SSc and 117 corresponding controls in CD4+ T cells." (PMID 31024609, 2019). "Although the relationship between CD8+ Tregs and CD4+ Tregs has not been clarified, the interaction seems to be fundamental to the prevention and cure of autoimmune diseases such as psoriasis." (PMID 31705000, 2019). "Contrary, other previous studies have suggested that microglia pre-activation does not interfere with autoimmune disease induced by CD4+ T cells." (PMID 30704526, 2019). "Our results reveal the importance of antigen non-related memory CD4+ T cells in autoimmune disease pathogenesis." (PMID 30755603, 2019). "Similarly, in autoimmune diseases, such as rheumatoid arthritis and systemic lupus erythematosus, miR-150 is less expressed in CD3+ T cells, and in particular CD4+ T cells." (PMID 30984166, 2019). "In addition to CD4+ Tregs, CD8+ Tregs possess important immunosuppressive functions and regulate Th17-mediated autoimmune diseases." (PMID 31394717, 2019). "Some authors have hypothesized that autoimmune diseases may develop in the first stage of infection, when the symptoms of HIV are few and CD4 count is still high." (PMID 31684052, 2019). "Meanwhile, the activation of self-reactive CD4+ T cells is necessary, although not sufficient, for inducing autoimmune diseases." (PMID 31709198, 2019). "During stage II (while declined CD4+ cell counts and immunosuppression are noted), autoimmune disorders are not typically found." (PMID 33324890, 2019). "This novel mechanism of autoimmune lymphopenia leading to CD4 T-cell depletion may have implication for the clinical management of patients with ALPS-FAS as well as other PIDDs and autoimmune diseases." (PMID 31191551, 2019). "Here we demonstrated an important novel role for RFX1 in the regulation of the increased IL-17A expression in CD4+ T cells of patients with SLE, as well as in the differentiation of Th17 cells and the development of the IL-17-related autoimmune diseases EAE and lupus in mice." (PMID 29422534, 2018). "Therefore, altered control of CD4+ and CD8+ T cells in their response to self-Ag is expected to significantly impact outcomes of autoimmune diseases." (PMID 30327657, 2018). "It remains to be elucidated if the aging-related effects on CD161+ CD4+ T cells and CD161high CD8+ T cells might be advantageous in the context of autoimmune diseases." (PMID 29725326, 2018).